TMEM179B (transmembrane protein 179B)
Tractability: Antibody: its Gene Ontology location is reachable by antibodies, with high confidence; UniProt predicts a signal peptide or a membrane-spanning region.
Gene: Protein-coding gene on chromosome 11 (62,787,387 to 62,790,403, forward strand). Ensembl gene ENSG00000185475.
Subcellular location: Membrane
Subcellular location (Human Protein Atlas): Nuclear speckles
Pathways (Reactome):
Immune System: Neutrophil degranulation
Gene Ontology:
Molecular function: protein binding
Cellular component: nuclear speck; azurophil granule membrane; ficolin-1-rich granule membrane; plasma membrane; secretory granule membrane; membrane
Genetic constraint (gnomAD): Loss-of-function variants: 15 observed, 18.85 expected, observed/expected ratio (o/e) 0.8, 90% interval 0.53 to 1.23. The synonymous counts are far from expectation, so gnomAD's model fits this gene poorly and the ratio says little. Missense variants: 320 observed, 259.77 expected, observed/expected ratio (o/e) 1.23, 90% interval 1.12 to 1.35. Synonymous variants: 159 observed, 116.94 expected, observed/expected ratio (o/e) 1.36, 90% interval 1.19 to 1.55.
Homologues: Orthologues: chimpanzee TMEM179B (100% identical), macaque TMEM179B (95% identical), rabbit TMEM179B (89% identical), dog TMEM179B (88% identical), pig TMEM179B (84% identical), guinea pig TMEM179B (83% identical), mouse Tmem179b (80% identical), rat Tmem179b (80% identical), zebrafish tmem179bb (40% identical), zebrafish tmem179ba (38% identical).